INS (insulin)
Diseases named in the same sentence as INS in open-access papers (continued):
Sharing a sentence is not in itself a finding about the gene and the disease.
diabetes (continued). "On the other hand, metformin, a first-line therapy for type 2 diabetes mellitus, activates AMPK indirectly by increasing the AMP/ATP ratio, thereby enhancing insulin sensitivity and reducing hepatic glucose production." (PMID 40450326, 2025). "Insulin resistance, a key component of metabolic syndrome and type 2 diabetes mellitus (T2DM), is defined as a decreased response to insulin that often requires higher insulin levels to achieve the integrated glucose‐lowering response." (PMID 40955380, 2025). "In addition, studies on rats have shown that they are highly effective in improving diabetes mellitus (DM) symptoms and increasing insulin sensitivity, reducing body weight, and modulating intestinal microbiota and lipid metabolism." (PMID 41321944, 2025). "Diabetes was induced by an intraperitoneal (i.p.)injection of STZ, with low-dose insulin given subcutaneously (s.c.)to manage mortality." (PMID 39846251, 2025). "Not only is it a very useful sign of the diabetes subtype of KPT2D but it is also the best predictor of short- and long-term independence from insulin." (PMID 38240751, 2024). "The most common is type 2 diabetes mellitus (T2DM), usually in adults, which occurs when the body becomes resistant to insulin or doesn't make enough insulin due to lifestyle imbalance." (PMID 38963109, 2024). "The Diabetes Control and Complications Trial (DCCT) demonstrated that intensive insulin therapy aimed at reducing hyperglycemic excursions delays the onset and retards the progression of microvascular complications." (PMID 39342285, 2024). "As HCV-infected persons can be complicated with diabetes, we further used glucose to stimulate HCV-infected cells and found that after the HCV infection, glucose uptake of the cells was inhibited and insulin secretion was reduced." (PMID 37962815, 2024). "Type 1 Diabetes Mellitus (T1DM) is a chronic autoimmune disease that results in the destruction of pancreatic β cells, leading to hyperglycaemia and the need for lifelong insulin therapy." (PMID 39408940, 2024). "Type 2 diabetes mellitus (T2DM) affects how your body uses sugar (glucose) for energy and stops the body from using insulin properly, which can lead to high levels of blood sugar if not treated." (PMID 39077252, 2024). "Furthermore, healthy African Americans adults with a family history of diabetes show significantly lower insulin sensitivity than their non-Hispanic Whites counterparts, highlighting ethnicity as a major determinant of peripheral insulin sensitivity and greater hepatic glucose output." (PMID 39125938, 2024). "Type-2 Diabetes Mellitus (T2DM) is a long-term metabolic condition marked by hyperglycemia due to decreased insulin production, insulin resistance, or both." (PMID 39453515, 2024). "Fifty-six male Sprague–Dawley rats (250–300 g) were assigned to eight groups: control, diabetes, and six diabetic groups receiving early or late treatments with WJMSCs-CM (D-CME, D-CML), insulin (D-INSE, D-INSL), or DMEM (D-DME, D-DML)." (PMID 39391856, 2024). "The most prescribed pre-index diabetes medications include metformin (75.1%), GLP-1 RAs (excluding OW sema T2D, 54.3%), and insulin (53.5%)." (PMID 39507603, 2024). "A recent study of the diabetes prospective follow‐up (DPV) initiative analyzed individuals with ABCC8‐MODY or KCNJ11‐MODY and reported a switch from insulin to oral sulfonylureas in most persons while maintaining good metabolic control." (PMID 39511990, 2024). "Another study reported that the addition of NMN to mice with diabetes led to notable improvement in their levels of NAD+, insulin sensitivity, and glucose tolerance." (PMID 37548938, 2024). "In diabetes, SIRT1 enhances insulin sensitivity by deacetylating insulin receptor substrate 2 (IRS2), which boosts the insulin regulatory pathway." (PMID 38931292, 2024). "MG15 lEVs and sEVs induced insulin-induced AKT hyper-phosphorylation and accumulation of triacylglycerol in myotubes, a state observed in pre-diabetes." (PMID 38539237, 2024).
diabetes (continued). "In diabetes, IR, reduced functional β-cell mass, and high levels of FFA in the blood work together with hyperglycemia, elevated insulin levels, fat accumulation, oxidative stress, and liver inflammation." (PMID 39728453, 2024). "It is utilized by patients with type 2 diabetes mellitus (T2DM), a condition characterized by elevated blood sugar levels due to the body’s impaired production or utilization of insulin." (PMID 38473837, 2024). "Key areas of investigation include expanding drug targets, stem cell therapies to regenerate insulin-producing beta cells in T1DM, microbiome-based interventions, and gene therapies for monogenic forms of obesity and diabetes." (PMID 38686257, 2024). "However, impaired secretion of insulin or the existence of insulin resistance (IR) in the peripheral tissues results in chronic hyperglycemia, which leads to the manifestation of impaired glucose homeostasis and the development of metabolic diseases, such as type 2 diabetes mellitus (T2DM)." (PMID 39272602, 2024). "While there are arguments that insulin therapy could increase the risk of CVD in type 2 DM, the increased risk of CVD in insulin users and those taking ≥ 3 oral GLDs suggests that insulin use should be interpreted as a marker of diabetes progression or severity." (PMID 38366387, 2024). "Additionally, although our definition of diabetes may have allowed inclusion of both type 1 and type 2 diabetes, the proportion of patients older than 30 years receiving insulin as their first treatment was 1.8%, indicating that over 98% of patients included in the analysis had type 2 diabetes." (PMID 38175642, 2024). "We also identified four key features highly effective in SH prediction: fasting plasma glucose (FPG), hemoglobin A1c (HbA1c), general diabetes education (g1diabed), and use of NPH or L Insulins (NPHL insulin)." (PMID 39349500, 2024). "During that period, he underwent an evaluation for diabetes, and the results of his tests, which included hemoglobin A1C (HbA1c) (5.4), C-peptide, anti-GAD, and anti-insulin antibodies, were all found to be within normal limits." (PMID 39634998, 2024). "Diabetes mellitus (DM) is a group of metabolic diseases characterized by hyperglycaemia (increased blood glucose levels) either due to defects in insulin secretion, insulin action, insulin resistance, or both." (PMID 37823574, 2024). "Insulin and glucagon‐like peptide (GLP)‐1 replenishment or improvement of insulin resistance are the two major strategies to treat diabetes." (PMID 38751366, 2024). "Additionally, agents that inhibited hepatic fat synthesis and stimulate the oxidation of skeletal muscle and adipose tissue (such as adipose and anti-obesity agents) could reduce ectopic lipid accumulation, improve insulin sensitivity, and ultimately prevent or delay the onset of diabetes." (PMID 39737158, 2024). "Emerging research highlights the link between AD and type 2 diabetes mellitus (T2DM), suggesting that shared pathophysiological mechanisms, such as insulin resistance, inflammation, and oxidative stress, contribute to both conditions." (PMID 39493064, 2024). "A significant reduction in insulin level and a significant elevation in FBG and FTA levels were noticed after diabetes induction in GI (1.6 ng/ml, 325.1 mg/ml and 307.3 μmol/l, respectively)." (PMID 38461158, 2024). "A thorough examination of the use of these biosensors in detecting diabetes mellitus, focusing on pivotal biomarkers like glucose, HbA1c, GHSA, and insulin, provides invaluable insights." (PMID 39091901, 2024). "Of note, compared with the Diabetes specialist clinics, use of SGLT2 inhibitors (13.2% versus 43.2%), GLP1-RAs (1.0% versus 6.2%), DPP4 inhibitors (15.4% versus 47.9%), and insulin (27.7% versus 58.1%) were lower in the General medicine clinics." (PMID 38166049, 2024). "Mice seem more likely to exhibit insulin resistant than rats, and C57BL/6 strain is more pronounced in the diabetes-prone strain than in the BALB/cByJ strain." (PMID 38846566, 2024).
diabetes (continued). "It is known that pasireotide treatment can lead to hyperglycaemia and impaired insulin secretion; hence, when observing cardiac abnormalities in patients undergoing pasireotide treatment, the causative factor may predominantly be diabetes rather than acromegaly." (PMID 38847918, 2024). "CPPs significantly reduced serum blood glucose, insulin level and MDA content increased SOD activity, and significantly improved insulin resistance of diabetes mice." (PMID 39624060, 2024). "Diabetes mellitus (DM), fasting blood sugar (FBS), oral antidiabetic drug (OAD) usage rate, and insulin usage rate were high in patients receiving ETV treatment." (PMID 39421537, 2024). "In the STZ-induced diabetes model, FAK AKO mice exhibit less serum insulin content and pancreatic β cell area." (PMID 38925910, 2024). "In patients with diabetes and HD whose average baseline blood glucose level was 8.3±2.5 mmol/L measured by CGM, they were followed up by SMBG and CGM to guide their diet or insulin therapy." (PMID 39628691, 2024). "It is noteworthy that the development of hyperglycaemia and impaired glucose-stimulated insulin secretion in high-fat-diet (HFD)-induced obesity models occur over a period of time, akin to the mild progression of diabetes observed in humans." (PMID 38182909, 2024). "Diabetes was uncontrolled in 214 (86%) patients, 165 (66%) patients were on oral hypoglycemic agent (OHA) alone, and 77 (31%) were on OHA plus insulin." (PMID 39233978, 2024). "The most common diabetes drugs were Biguanides (Metformin), DPP-4 inhibitors, GLP-1 agonists, Insulin, SGLT-2 inhibitors, and Sulfonylurea." (PMID 39759947, 2024). "It is likely that some of the detrimental effects of Ang II in obesity and diabetes mellitus are mediated by aldosterone, which closely cooperates with RAS and participates in the regulation of insulin secretion." (PMID 38279313, 2024). "Type 2 diabetes mellitus (T2DM) is characterized by increased insulin resistance (IR), insulin insensitivity, and blood glucose levels and is becoming increasingly prevalent worldwide." (PMID 38397668, 2024). "One of the first steps towards diabetes is the inhibition of IRS, PI3K, or Akt in the PI3K-Akt signaling pathway, which leads to insulin resistance, although the exact process leading to the development of T2DM has not yet been fully elucidated." (PMID 39123454, 2024). "The use of diabetes technology such as continuous glucose monitoring (CGM) and automated insulin delivery (AID) systems in outpatient settings is growing." (PMID 38953925, 2024). "Although general knowledge of diabetes was classified as "medium" for most patients, this level of knowledge may not be sufficient to ensure good self-care, especially in more vulnerable groups, such as insulin-treated patients and those with a longer duration of disease." (PMID 39791030, 2024). "The SII was calculated, and the markers of diabetes such as fasting blood glucose (FBG), insulin, and hemoglobin A1c (HbA1c) were included." (PMID 38541168, 2024). "Methylated trivalent arsenic such as MMAIII and DMAIII can reduce glucose-stimulated insulin secretion (GSIS) by impairing calcium influx stimulated by glucose, thereby playing a significant role in diabetes." (PMID 39135557, 2024). "Type 1 diabetes mellitus (T1DM) is a chronic and notably severe medical condition that is recognized for its defining feature of an inadequate production of insulin by the pancreatic β-cells." (PMID 38256380, 2024). "Different from most previous studies focusing on TCS exposure and diabetes, we not only included T2DM as the outcome but also glucose metabolism-related indicators (FBG, INS, HbA1c, HOMA2-β, and HOMA2-IR)." (PMID 39596180, 2024). "One subject had a well‐controlled diabetes mellitus (DM) type 1, wherefore insulin treatment." (PMID 39323922, 2024).
diabetes (continued). "Type 2 diabetes mellitus (T2DM) is characterized by a gradual reduction of insulin production from the pancreatic β-cell because of β-cell dysfunction and insulin resistance in the target organs which ultimately turns to chronic hyperglycaemia." (PMID 39170471, 2024). "Male mice were chosen for this project to avoid experimental variability related to female hormonal effects on insulin sensitivity and to exploit the higher rate of development of STZ-induced diabetes in male compared to female mice." (PMID 38659015, 2024). "If we can accurately differentiate a type of diabetes in the newly diagnosed diabetic patients who presented with DKA, the appropriate monitoring and management, including discontinuation of insulin, will be implemented." (PMID 39010018, 2024). "In this area, Santos’s lab has reported the use of pSi for oral delivery of insulin and glucagon-like peptide-1 (GLP-1) for the management of diabetes." (PMID 38819767, 2024). "The primary subtypes are Type 1 diabetes mellitus (T1DM) and Type 2 diabetes mellitus (T2DM), which typically arise from impaired insulin secretion (T1DM) and/or insulin function (T2DM)." (PMID 38988858, 2024). "Large commercial plans and pharmacy benefit managers (PBMs) also offer plans with insulin OOPC limits and/or support value‐based designs with low or reduced OOPC for diabetes medications including insulin." (PMID 36992575, 2024). "ADAMTS6 encodes a secreted metalloprotease, and showed the alleviating effect of insulin on diminishing ADAMTS6 levels in human cell lines, suggesting a weak link with diabetes." (PMID 39072272, 2024). "Various biomarkers have been used to detect diabetes mellitus, such as glucose, HbA1c, GHSA, and insulin, with various methods developed, such as ion exchange chromatography, affinity chromatography, capillary electrophoresis, enzymatic assay, and immunoassay." (PMID 39091901, 2024). "Fasting hyperglycemia, as seen in our cachectic patients, also defines type 2 diabetes mellitus (T2DM) and is largely secondary to inadequate action of the major glucose-lowering hormone insulin." (PMID 38450189, 2024). "Medications, including insulin, metformin, sulfonylureas, and GLP-1 receptor agonists, are commonly used to help manage diabetes." (PMID 39300573, 2024). "These advances were a breakthrough in diabetes technology, increasing the use of CGM7 and leading the way for the development of automated systems for insulin delivery." (PMID 39306610, 2024). "The guidelines by the Joint British Diabetes Societies for Inpatient Care in 2022 recommend resolving the metabolic acidosis in patients with DKA by intravenous fluid and insulin." (PMID 39768744, 2024). "Individuals with basal-insulin initiation, as compared to NIAD only treated, were a bit younger, had longer diabetes duration and higher levels of HbA1c." (PMID 38116986, 2024). "The cooperation between these peptides and insulin is emphasized, drawing attention to the aberrant interactions of RAS and AVP with insulin in diabetes mellitus and other metabolic disorders." (PMID 38279313, 2024). "It has been reported that the combined administration of insulin and NAC showed myocardial protection for canines with diabetes by promoting the linear ubiquitination of receptor-interacting protein kinase 1 (RIPK1) and NF-κB-essential modulator (NEMO)." (PMID 39339978, 2024). "The Diabetes Attitudes, Wishes, and Needs (DAWN) study can be used to assess patients’ attitude of insulin treatment." (PMID 39036047, 2024). "In terms of managing diabetes, the BRFSS described health-promoting behaviors of taking insulin, checking blood glucose daily, checking feet, and checking hemoglobin A1C (HbA1c) yearly." (PMID 40125368, 2024). "Nevertheless, the most crucial aspect of CGM lies in monitoring glucose trends and adjusting insulin dosages based on CGM data, facilitating better therapeutic decision-making and preventing hypoglycemia, a central objective in diabetes management." (PMID 37930420, 2024).
diabetes (continued). "Instead, AQP8-overexpressing cells showed higher proliferative features and increased insulin content, highlighting the role of AQP8 in H2O2 homeostasis in pancreatic β-cells and the development of type-1 diabetes mellitus." (PMID 39125952, 2024). "Studies have shown that in animal models of diabetes, ASBT inhibitors can effectively improve insulin sensitivity, reduce blood glucose and increase insulin levels." (PMID 39850557, 2024). "The strong positive correlation between obesity/diabetes and increased muscle TET3 expression in both humans and mice suggests a role for TET3 in regulation of muscle insulin sensitivity." (PMID 38216792, 2024). "Type 2 diabetes mellitus (T2DM) is a chronic metabolic disease characterized by hyperglycemia, insulin resistance, and insufficient insulin secretion." (PMID 38640276, 2024). "Polyphenols have been shown to reduce hyperglycemia, enhance acute insulin secretion and insulin sensitivity, and are utilized as a treatment to improve PCOS symptoms and effectively manage diabetes." (PMID 39064680, 2024). "Medtronic pioneered integrated diabetes management with the MiniMed Paradigm REAL-Time system in 2006, blending an insulin pump with continuous glucose monitoring (CGM)." (PMID 39065641, 2024). "Type 2 diabetes mellitus (T2DM) is a chronic metabolic disorder characterized by high blood glucose levels resulting from insulin resistance and impaired insulin secretion." (PMID 38455849, 2024). "The findings underscore the importance of tailored insulin therapy for children with newly diagnosed T1DM and highlight the need for vigilant monitoring of body weight as a part of comprehensive diabetes management." (PMID 38590482, 2024). "In our present investigation, we delved into the correlation between glucose levels and heart rate parameters, examining their association with bradycardia events in 19 patients diagnosed with both diabetes and CKD who were undergoing insulin treatment." (PMID 39638855, 2024). "In type 2 diabetes mellitus (T2DM), cells in the body become resistant to the action of insulin, and the pancreas is unable to make enough insulin to overcome this resistance." (PMID 38279951, 2024). "The median duration of diabetes was 14 years (IQR, 7–19 years), with 30% of the patients being treated by insulin therapy." (PMID 39337027, 2024). "Given that IGFBP7 is upregulated in human pancreatic islets in type 2 diabetes, and that reversing this improves insulin secretion, IGFBP7 is emerging as a possible multi-tissue drug target in diabetes and other metabolic disorders." (PMID 39280605, 2024). "The changes in glucose homeostasis, lipid metabolism, and insulin sensitivity are common alterations characterized in both MASLD and diabetes." (PMID 39470335, 2024). "Conventional treatments for the management of obesity and diabetes, including metformin GLP1 receptor agonists and TZDs, lead to improvements in insulin sensitivity and provide anti-inflammatory benefits." (PMID 39199336, 2024). "Type 2 diabetes mellitus (T2DM) is characterized by chronic hyperglycemia due to decreased insulin secretion by pancreatic beta cells and increased insulin resistance." (PMID 39897957, 2024). "Type 2 diabetes mellitus (T2DM) is a complex metabolic disorder marked by both insulin resistance and impaired insulin production." (PMID 39618608, 2024). "STUB1 has been shown to regulate diabetes through the degradation of INSR, and we demonstrated another mechanism to control insulin signaling." (PMID 38970167, 2024). "Type 1 diabetes mellitus (T1DM), also called insulin-dependent diabetes mellitus, is an autoimmune disease in which insulin-producing pancreatic β-cells are destroyed, resulting in an absolute insulin deficiency." (PMID 39224109, 2024).